REN (renin)
Diseases named in the same sentence as REN in open-access papers (continued):
Sharing a sentence is not in itself a finding about the gene and the disease.
Primary hyperaldosteronism (continued). "Primary hyperaldosteronism (PHA) involves excessive aldosterone secretion that is independent of normal physiological regulation by the renin‐angiotensin system, with suppression of renin activity due to the resulting extracellular volume expansion." (PMID 40813337, 2025). "In some cats, the diagnosis of primary hyperaldosteronism was made in the absence of renin measurements." (PMID 39429164, 2024). "Primary hyperaldosteronism was ruled out as plasma aldosterone levels were <10 ng/dL despite of elevated aldosterone/renin ratio." (PMID 39184766, 2024). "Especially, primary hyperaldosteronism should be ruled out using appropriate screening tests under standardised conditions consisting of measurement of plasma renin activity (or concentration) and serum aldosterone to calculate the aldosterone-to-renin ratio." (PMID 36001280, 2023). "In addition to the lack of adrenal tumor, the markedly increased plasma renin activity was atypical for primary hyperaldosteronism." (PMID 34859924, 2021).
ischemia (36 papers, 2007 to 2025). A hypoperfusion of the BLOOD through an organ or tissue caused by a PATHOLOGIC CONSTRICTION or obstruction of its BLOOD VESSELS, or an absence of BLOOD CIRCULATION. "This approach is functionally relevant since opposite changes in renin cell granularity and plasmatic levels of C14-labeled quinacrine were documented in circumstances associated with high renin secretion rates (i.e., hemorrhage and ischemia,)." (PMID 20948562, 2010). "Goldblatt (1934) demonstrated that occlusion of the renal artery causes ischemia, which then causes an elevation of blood pressure by triggering the release of renin." (PMID 17672905, 2007). "This, coupled with excessive activation of the local renin-angiotensin system, ultimately leads to renal parenchymal ischemia, atrophy, fibrosis, and even necrosis." (PMID 41487498, 2025). "In acquired heart diseases, activation of cell signaling systems, such as activation of natriuretic peptides and the renin-angiotensin-aldosterone system, occurs in response to ischemia or abnormal cardiac distension resulting from pressure or volume loading." (PMID 40373525, 2025). "During MI, ischemia and injury trigger a series of molecular and cellular responses, notably the activation of the renin–angiotensin system (RAS)." (PMID 39834616, 2025). "This hypoxia triggers a compensatory response through activation of the sympathetic nervous system and the renin–angiotensin–aldosterone system, leading to increased heart rate and blood volume, which overload the heart and worsen ischemia." (PMID 40429500, 2025). "This ischemia triggers sympathetic nervous system activation and cascade involving the circulating renin-angiotensin system, leading to systemic vasoconstriction, irreversible myocardial damage, and reduced cardiac ejection capacity." (PMID 37815980, 2023). "In contrast, another cytosolic renin isoform named renin-b has been described, exerting protective effects under ischemia-related conditions in H9c2 cardiomyoblasts." (PMID 35563765, 2022). "PexRAP endothelial knockout (PEKO) mice responded normally to hindlimb ischemia but had lower blood pressure and increased plasma renin activity." (PMID 33894211, 2021). "We and others reported that ns-renin increases in the myocardium after myocardial ischemia and is involved in cardiac protection during ischemia." (PMID 29295576, 2017). "In addition, in human renin and angiotensinogen double transgenic mice, the activation of human Ras enhances ischemia-induced brain injury by significantly reducing cerebral blood flow and enhancing oxidative stress." (PMID 35378910, 2022). "The direct vasoconstrictor effects of iohexol and further exacerbation of ischemia are significant because the vasoconstricting molecules, including renin, endothelin, and adenosine, increase and the vasodilatory molecules such as prostaglandin and nitric oxide decrease." (PMID 32500677, 2020). "Our results cannot clearly identify whether activated ERK1/2 was translocated from cytosolic space or mitochondrial ERK1/2 was activated on the surface of mitochondria by int-renin accumulation during ischemia." (PMID 29295576, 2017). "Although we studied Goto-Kakizaki rat hearts as the type II DM model, we assume that int-renin may have some contribution to protect heart from ischemia in type I model animals as well." (PMID 29295576, 2017). "Although the precise mechanism remains unclear, ns-renin is considered to supply cardiac protection during ischemia." (PMID 29295576, 2017). "Relative gene expression of α-klotho and renin-angiotensin system (RAS) compounds after 90 days evaluated in Control rats (C), Vitamin D deficient rats (VDD), rats submitted to Ischemia/Reperfusion Injury (IRI), and Vitamin D deficient rats submitted to Ischemia/Reperfusion Injury (VDD+IRI)." (PMID 25222475, 2014). "However, the precise mechanism by which increased ns-renin protects the heart from ischemia remains unclear." (PMID 29295576, 2017).
ischemia (continued). "In addition, activation of the renin angiotensin system stimulates renin secretion by the kidneys; it also leads to dysregulation of extracellular fluid volume and vasoconstriction which can exacerbate the effects of ischemia by limiting adequate oxygen delivery." (PMID 26478820, 2015). "This can activate the renin-angiotensin system (RAS) and induce pre-glomerular arteriolar disease characterized by arteriolar wall thickening and hyalinosis, thereby promoting ischemia." (PMID 39011045, 2024). "At the same time, hydration therapy can also inhibit the renin-angiotensin-aldosterone system (RAAS), increase NO, dilate blood vessels and reduce medulla ischemia." (PMID 34295921, 2021). "The natriuretic peptide (NP) system counter‐regulates the renin‐angiotensin system (RAS), so enhancing the activity of natriuretic peptides (NPs) may be beneficial in conditions when RAS is activated such as ischemia‐reperfusion injury (IRI)." (PMID 33719192, 2021). "In summary, we present a new prominent protective effect of non-secretory renin which is manifested under ischemia-relevant conditions and may act in a preconditioning-like manner." (PMID 32047214, 2020). "Although beneficial effects of non-secreting intracellular renin (ns-renin) against ischemia have been reported, the precise mechanism remains unclear." (PMID 29295576, 2017). "In addition, smoking induces coronary vasoconstriction, stimulates the renin-angiotensin system, and increases inflammatory cytokines (e.g., interleukin-6 (IL-6), tumor necrosis factor-alpha (TNF-α)), contributing to plaque development, instability, and ischemia." (PMID 41306139, 2025).
depression (34 papers, 2013 to 2025). "Cigarette smoke is atherogenic, vasculotoxic and pro-inflammatory causing the release of cytokines that activate the renin-angiotensin-aldosterone pathway with resultant adverse haemodynamics and myocardial toxicity and depression." (PMID 33493215, 2021). "Drugs targeting the renin–angiotensin system act on inflammatory pathways implicated in depression." (PMID 28760142, 2017). "Depression may have multi-pathogenic causes and may be related to disturbances of the hypothalamic pituitary axis, the renin angiotensin aldosterone system, the central nervous system, oxidative stress, increased inflammation, and the presence of genetic factors." (PMID 25036781, 2014). "In addition, renin–angiotensin system activity has been associated with hyperactivity of the hypothalamic–pituitary–adrenal axis and may have direct neurotoxic effects that may contribute to depression." (PMID 35388727, 2022). "In stress situations such as depression and anxiety, the renin-angiotensin-aldosterone system is activated with increased sympathetic activity." (PMID 36397079, 2022). "In humans, increased basal renin and/or plasma aldosterone concentrations have been observed in post-traumatic stress disorder and depression as psychiatric disorders discussed in the context of chronic stress." (PMID 31711229, 2020). "Interventions, which reduce the activity of the renin–angiotensin aldosterone system, have been demonstrated to influence major depression." (PMID 33362613, 2020). "Brain insulin signaling is accounted for the development of a variety of neuropsychiatric disorders, such as anxiety and depression, whereas both inflammation and the activated renin-angiotensin system (RAS) are two major contributors to insulin resistance." (PMID 31001119, 2019). "Arginine vasopressin has been suggested to contribute to anxiety and depression, and the renin–angiotensin–aldosterone system via angiotensin 1a receptors, has a role in a stress response that involves the hypothalamic–pituitary–adrenal axis." (PMID 31450591, 2019). "Renin-angiotensin system takes parts in both onsets of depression, the emergence of anhedonia, and response to an antidepressant." (PMID 31856805, 2019). "Total sleep deprivation in patients with depression leads to an increase in renin secretion and a concomitant trend for a decrease in the hypothalamic–pituitary–adrenal axis activity next night." (PMID 26466096, 2015). "The treatment with GG extract or its active components may, therefore, be a useful adjunct therapy for patients with subtypes of depression and anxiety disorders with heightened renin–angiotensin–aldosterone system and/or inflammatory activity." (PMID 38398838, 2024). "The investigators found that continued use of classes of CCBs, renin-angiotensin system agents, and β-blockers was associated with a decreased risk of depression, whereas diuretic use was not." (PMID 38800057, 2024). "Excessive activation of the renin-angiotensin system pathway can lead to disturbances in the internal environment, increased reabsorption of Na+ by the renal tubules, and elevated levels of renin and angiotensin, leading to elevated blood pressure, insomnia, anxiety, depression, and inflammation." (PMID 38784223, 2024). "Inflammatory state:Depression-(pw7b)-central nervous system-(pw27)-↑cortisol-(pw48)-liver-(pw14)-↑blood glucose-(pw54)-PI3K:MAPK-(pw69)-↑insulin resistance-(pw70)-↑angiotensin II-(pw88)-renin-(pw50)-↑TNFα-(pw41)-↑Inflammatory state." (PMID 35252372, 2022). "Conversely, pathological mechanisms shared by the kidney and brain tissue damage, such as the renin–angiotensin system, may contribute to cerebrorenal interactions and exacerbate depression in patients with CKD." (PMID 35361150, 2022). "Aliskiren, a renin inhibitor, is proven to be an alternative for the treatment of neuroinflammation by suppressing microglial cell activation and proinflammatory cytokine generation, which prevent the development of depression." (PMID 35625041, 2022).
depression (continued). "There is now evidence that the renin–angiotensin system, especially in the brain, plays an important role in cognition, depression, and behavior and that inhibition of the renin–angiotensin system may have therapeutic potential in mood disorders." (PMID 27733585, 2016). "The observation that captopril induced an antidepressant effect in hypertensive patients led to the suggestion that the brain renin-angiotensin system (RAS) may be involved in depression, and inhibition of the RAS may have antidepressant effect." (PMID 25423262, 2014). "Moreover, patients who suffer from depression have activation of the hypothalamic-pituitary-adrenal axis and the renin-angiotensin-aldosterone system." (PMID 23710335, 2013). "Notably, the renin–angiotensin system (RAS) is involved in the pathogenesis of depression, and different findings revealed that angiotensin‐converting enzyme inhibitors (ACEIs) and angiotensin receptor blockers (ARBs) may be effective in depression." (PMID 37953501, 2024). "Furthermore, depression may activate the renin-angiotensin system, further elevating blood pressure." (PMID 37598204, 2023). "However, some elements of depression such as hormones and receptors of the renin–angiotensin–adrenal system (RAAS), the hypothalamus–pituitary–adrenal (HPA) axis, and history of early-life stress (ELS) could be considered for differential diagnosis." (PMID 36358401, 2022). "ACE Inhibitors (ACEIs), which target the renin-angiotensin system (RAS), are thought to offer protective benefits for cognition, depression, and anxiety." (PMID 39184138, 2024). "A cursory literature search reveals physiological arguments that the renin‐angiotensin system (on which ACE inhibitors act) plays an important role in mood disorders, as well as case studies dating back to the 1980s of ACE inhibitors appearing to treat major depression." (PMID 35689299, 2022). "However, this study suggests that ACEI or ARBs that modulate systemic renin–angiotensin system activity do not have a protective effect on the development of depression in older individuals." (PMID 35388727, 2022).
acute respiratory distress syndrome (28 papers, 2017 to 2026). Progressive and life-threatening pulmonary distress in the absence of an underlying pulmonary condition, usually following major trauma or surgery. "ACE2 plays a crucial role in the pathogenesis of severe acute lung injury, as downregulating its expression reduces lung damage, regulates the renin-angiotensin pathway, and mitigates acute respiratory distress syndrome (ARDS) symptoms." (PMID 37809955, 2023). "The renin-angiotensin system (RAS) maintains blood pressure and electrolyte balance in the body and has also been implicated in the pathogenesis of acute respiratory distress syndrome (ARDS)." (PMID 35743089, 2022). "In vivo, the peptidase activity of ACE2 has been shown to suppress the renin-angiotensin system (RAS system) to improve cardiovascular or kidney diseases as well as acute respiratory distress syndrome (ARDS)." (PMID 35003058, 2021). "The most devastating complication of this disorder is the Acute Respiratory Distress syndrome (ARDS) which is thought to be caused by a mixture of mechanisms among them are cytokine storm, abnormal activity of the renin-angiotensin apparatus, neutrophil stimulation and enhanced coagulation." (PMID 34147082, 2021). "Renin-angiotensin system (RAS) signaling and angiotensin-converting enzyme 2 (ACE2) have been implicated in the pathogenesis of acute respiratory distress syndrome (ARDS)." (PMID 28877748, 2017). "Results from preclinical studies suggest that age-dependent differences in host defense and the pulmonary renin–angiotensin system (RAS) are responsible for observed differences in epidemiology of acute respiratory distress syndrome (ARDS) between children and adults." (PMID 31089908, 2019). "A recent study performed on a mouse model proposes the modulation of the renin-angiotensin pathway as a therapeutic target to protect individuals with SARS-CoV-2 infection from developing acute severe lung failure and acute respiratory distress syndrome." (PMID 33668011, 2021). "The physiological effects of renin-angiotensin system modulation in acute respiratory distress syndrome (ARDS) remain controversial and have not been investigated in randomized trials." (PMID 38103056, 2023). "During the pulmonary phase, SARS-CoV-2 infects the host cells by binding the ACE2 receptor, impairing its role in regulating the renin-angiotensin system (RAS), and starting an acute respiratory distress syndrome (ARDS)." (PMID 41500120, 2026). "Notably, in animal models of microbial acute lung injury (ALI) and acute respiratory distress syndrome (ARDS), the renin–angiotensin system (RAS) was central to the pathogenicity, as it affected the vascular tone and permeability in addition to the fibroblast activity and alveolar cell survival." (PMID 36890344, 2023).
type 1 diabetes (27 papers, 2009 to 2026). "Even though it remains an important cause of mortality in type 1 diabetes mellitus (T1DM) patients, vitamin D (VD) acts on renin–angiotensin system, inflammatory cascade, and vasculature." (PMID 28855892, 2017). "One randomized controlled trial reported that paricalcitol significantly improved renal function in type 1 diabetes patients with renal impairment when combined with renin-angiotensin-aldosterone system (RAAS) blockers." (PMID 36994344, 2021). "One of the eight patients with type 1 diabetes used a renin–angiotensin system blocking agent (lisinopril), which was temporarily discontinued during the study (as indicated in the Research design and methods section)." (PMID 32404378, 2020). "Vitamin D may also have a direct effect on the renin-angiotensin-aldosterone-system and the renin-angiotensin-aldosterone-system is known to be overexpressed in patients with type 1 diabetes and retinopathy and blockade of this system reduces DR progression." (PMID 26885530, 2016). "Although many questions remain unanswered regarding the GLP-1 analogue, Exendin-4 and the renin-inhibitor, Aliskiren, it is evident that treatment with both Exendin-4, and Aliskiren greatly improves the GLP-1 binding affinity at the coronary endothelium level of the type 1 diabetic rat." (PMID 21747829, 2011). "Treatment with empagliflozin attenuated hyperfiltration in 37 people with type I diabetes not on RAS inhibition and resulted in an increase in urinary levels of angiotensinogen, ACE, ACE-2, rise in plasma angiotensin I, II and renin activity as well as a fall in plasma ACE activity." (PMID 36247425, 2022).